MMP7 (matrix metallopeptidase 7)
Diseases named in the same sentence as MMP7 in open-access papers (continued):
Sharing a sentence is not in itself a finding about the gene and the disease.
breast carcinoma (97 papers, 2004 to 2025). "Our findings showed that MMP7 rs11568818 A allele carriers were associated with better prognosis regarding lower chances for poorly differentiated breast cancer." (PMID 36009438, 2022). "Meanwhile, MMP7 rs11568818 was statistically significantly associated with poorly differentiated breast cancer in all three analyzed multivariate logistic regression models." (PMID 36009438, 2022). "The presence of the MMP7 rs11568818 A allele was associated with lower chances for poorly differentiated breast cancer." (PMID 36009438, 2022). "FOXC1 expression is significantly associated with expression of MMP7 in breast cancer samples and cell lines at both the mRNA and protein levels." (PMID 29552326, 2018). "In murine models of prostate and breast cancer osteolysis, MMP-7 deficiency was associated with a reduction in the cleavage of RANKL to a soluble form and a decrease in osteoclasts at the tumor:bone interface." (PMID 28241871, 2017). "The increase in myeloma tumor burden in response to a loss of host-derived MMP-7 is in distinct contrast to previous studies in prostate cancer and breast cancer osteolysis, where tumor burden and osteolytic bone disease were decreased in MMP-7 deficient mice." (PMID 28241871, 2017). "PLCD1 inhibits MMP7 expression, resulting in anti-tumour effects in gastric and breast cancers, but the underlying mechanism remains elusive." (PMID 28423710, 2017). "Novel findings presented in this pilot study include the observation that SNP rs1943779 in the MMP7 gene is associated with improved DDFS after breast cancer diagnosis." (PMID 19094228, 2008). "In this paper, we present a continuation of the evaluation of MMPs as new tumor markers for breast cancer, this time by assessing two metalloproteinases MMP-3 and MMP-7 as a diagnostic marker of early-stages breast cancer with Luminal A or Luminal B HER-negative subtypes." (PMID 37048701, 2023). "Given the suggested role of MMP-3 and MMP-7 in the pathogenesis of breast cancer and their diagnostic potential as demonstrated in research papers, we decided to test them as early tumor markers of breast cancer." (PMID 37048701, 2023). "Moreover, single nucleotide polymorphisms in MMP7 have been associated with disease free and/or overall survival in two breast cancer case control studies." (PMID 24304664, 2013). "Interestingly, MMP7 expression positively correlated with M1-like TAMs but negatively correlated with M2-like TAMs in breast cancer, implying that MMP7 overexpression may cause a shift toward an M1-like phenotype and contribute to better clinical outcomes." (PMID 40900789, 2025). "As it has been previously shown from our research group, MMP7 appears upregulated in 3D breast cancer spheroids (derived from shERβ MDA-MB-231 and Hs578T cells, respectively)." (PMID 41228316, 2025). "Bioinformatic analysis using cBioPortal v6.0.0, revealed a positive correlation between USP30-AS1 expression and several Wnt signaling components, including TCF7, WNT1, WNT10, and MMP7, in clinical breast cancer." (PMID 41614739, 2025). "In the case of breast cancer, there is a correlation between MMP-7 levels and cancer stages—higher levels of the marker are observed in stages III and IV compared to stage I." (PMID 40332487, 2025). "Myofibroblasts are important sources of MMPs in breast cancer, and tumour progression and adverse reactions are associated with strong expression of MMP-1, MMP-7, and MMP-9, as well as fibroblast-specific production of MMP-9, MMP-11, and MMP-1431." (PMID 38956273, 2024). "Basal-like breast cancer has upregulated MMP7 expression, which has been linked to DKK1 knockdown, a known tumor suppressor in breast cancer." (PMID 39057065, 2024). "It is worth noting, however, that in our team’s previous work, we observed an increase in plasma MMP-3 and MMP-7 concentrations in stage III–IV breast cancer patients when compared to patients who were found to be at stage I." (PMID 37048701, 2023).
breast carcinoma (continued). "MMP7 gene expression is correlated with tumor size, triple-negative (TN) status, and the recurrence of breast cancer." (PMID 37298519, 2023). "CCR10 expression was discovered to be elevated in breast cancer cells, and the CCL27/CCR10 axis eventually promoted breast cancer cell invasion and migration via elevating MMP-7." (PMID 36250005, 2022). "TM4SF1, as well, is known to be downregulated in hormone-positive tumours, while increased expression of MMP7 distinguishes the basal-like breast cancer subtype from other triple-negative tumours." (PMID 36536459, 2022). "The protein expression level of MMP7 was also found to be significantly lower in the primary tumor tissues of breast cancer (P < 0.05) and clear cell RCC (P < 0.001) when compared with normal tissues." (PMID 35785154, 2022). "We aimed to evaluate the contribution and association of single-nucleotide polymorphisms (SNPs) in MMP genes (MMP1, MMP2, MMP3, MMP7, MMP8, MMP9) with clinicopathological breast-cancer features." (PMID 36009438, 2022). "Many malignant tumors including gastrointestinal tumors, breast cancer, and head and neck tumors are found to have a high expression of MMP-7." (PMID 34621293, 2021). "Second, DBC1 activates the expression of MMP7, a mesenchymal cell marker, to pivot breast cancer cells to a more malignant phenotype by interacting with the zinc finger transcription factor ZFN326." (PMID 34631698, 2021). "Several reports have shown that MMP7 is overexpressed in both the cells and tissues of breast cancer." (PMID 31285694, 2019). "DKK1 suppressed breast cancer cell migration and invasion by alleviating β-catenin/MMP7, our findings offered a potential alternative for breast cancer prevention and treatment." (PMID 31285694, 2019). "Western blot and real time PCR was used to detect the expression of DKK1, β-catenin and MMP7 in breast cancer cells." (PMID 31285694, 2019). "DKK1 inhibits migration and invasion of breast cancer cell through suppression of β-catenin/MMP7 pathway, our findings offered a potential alternative for breast cancer prevention and treatment." (PMID 31285694, 2019). "An interesting observation is that in the breast carcinoma data MMP7 expression was elevated in a subset of tumor-matched normal tissues (grossly normal tissue obtained at the time of tumor resection) within TCGA dataset." (PMID 31882975, 2019). "The only references in such regard is that activation of NF-κB by Wnt5a was shown to be required for BMP-6 mRNA and MMP7 upregulation in LNCaP and breast cancer cells, respectively." (PMID 31510045, 2019). "Taken together, these results showed that DKK1 inhibits breast cancer migration and invasion through suppression of β-catenin/MMP7 signaling pathway." (PMID 31285694, 2019). "DKK1 suppressed breast cancer cell migration and invasion through suppression of β-catenin and MMP7 expression." (PMID 31285694, 2019). "Overexpression of DKK1 represses MMP7 expression and inhibits migration and invasion of breast cancer cells." (PMID 31285694, 2019). "Here, we demonstrate MMP7 is an important target downstream of DKK1 in breast cancer cells, based on the following studies: knockdown of DKK1 is associated with enhanced level of MMP7 in MDA-MB-231 and MCF-7 cells." (PMID 31285694, 2019). "Combination of FOXC1 expression with matrix metalloprotease 7 (MMP7) expression can be used as an independent predictor of patient outcome in multivariate analyses of two breast cancer patient cohorts." (PMID 29552326, 2018). "In this study, we found that PLCD1 was downregulated in breast cancers, and the gain-or-loss functional assay revealed that PLCD1 inhibited cell migration and invasion in vitro via the ERK1/2/β-catenin/MMP7 signalling pathway." (PMID 28423710, 2017). "Collectively, our findings suggest that PLCD1 acts as a tumour suppressor, by KIF3A-mediated suppression of ERK1/2/β-catenin/MMP7 signalling, at least in part, in breast cancer." (PMID 28423710, 2017).
breast carcinoma (continued). "MMP7 is a direct transcriptional target of β-catenin signaling and is regulated by β-catenin in human colorectal cancer, pancreatic cancer, and breast cancer." (PMID 29250491, 2017). "PLCD1 has been demonstrated to suppress MMP7 levels and thereby regulate cell migration in high-stage gastric and breast cancers." (PMID 28423710, 2017). "It is interesting that MMP7 protein levels were inhibited by PLCD1 in gastric and breast cancer in our previous work, even though the underlying mechanism is not known." (PMID 28423710, 2017). "It is well known that MMP7 is a downstream target of the Wnt/β-catenin signalling pathway that is activated in multiple cancers including breast cancers." (PMID 28423710, 2017). "Several MMPs have been reported to induce EMT, including MMP-3 in breast cancer, MMP-7 in gastric and lung cancer cell lines, MMP-9 in ovarian and squamous cancer cell lines, and MT1-MMP in an ischemic rat kidney cell line." (PMID 27374080, 2016). "Enhanced expression of MMP7 in MMTV-Ron VDR−/− mammary tumors and, conversely, reduced expression in R7 cells treated with 1,25D3 suggests a mechanism by which ligand-dependent VDR signaling delays tumor formation and mitigates progression." (PMID 26008979, 2015). "Expression of some MMPs correlated with FOXC1 expression, such as MMP7 in breast cancer and MMP1, MMP2, MMP7, and MMP9 in hepatocellular cancer." (PMID 24889262, 2014). "It has been reported previously that cleavage of annexin A2 at lysine 10 by MMP-7 can assist tumor invasion and metastasis of colorectal and breast cancer cell lines." (PMID 23945256, 2013). "The expression level of MMP-7 mRNA was higher in normal breast tissue than in breast cancer tissue, both in grade 2 (p = 0,008) and grade 3 (p = 0,04)." (PMID 19531263, 2009). "While the expression of MMP-7 mRNA was significantly lower in breast cancer tissue when compared to normal breast tissue." (PMID 19531263, 2009). "Equal to higher expression levels of MMP-7 pro and active forms in breast cancer tissue were detected." (PMID 19531263, 2009). "Relaxin has also been shown to enhance in-vitro invasiveness of breast cancer cells, where it increases the production of several metalloproteinases, including MMP-7." (PMID 17623071, 2007). "This is the first study showing a slight increase of circulating levels of MMP-7 in patients with breast cancer and bone metastases." (PMID 16880790, 2006). "Furthermore, within the course of different cancers such as breast cancer, elevated levels of MMP-7 have been found in cancer patients compared to healthy women." (PMID 41007705, 2025). "MMP7 gene functions as a proto-oncogene, driving breast cancer development and progression." (PMID 41228316, 2025). "Although MMP-7 expression has not been really associated with prognosis or outcomes of Luminal A breast cancer patients, our findings probably suggest that MCF-7 cells grown in 3D models undergo a transition towards a more invasive phenotype." (PMID 41228316, 2025). "Additionally, cell surface PGs (SDC1 and SDC4) and MMPs (MMP2, MMP7, MMP9, and MMP14) implicated in breast cancer progression were further included." (PMID 41228316, 2025). "Interestingly, zoledronate, a common drug used to treat bone damage and osteoporosis, has been shown to decrease the expression of MMP7 in breast cancer cell lines." (PMID 39057065, 2024). "The only report indicating serum MMP-7 levels changes in relation to molecular subtype showed that elevated levels were associated with breast cancer subtypes with worse prognosis, that is, receptor-negative and HER2 receptor-positive subtypes." (PMID 37048701, 2023). "The role of matrix metalloproteinase-3 (MMP-3) and (MMP-7) in the pathogenesis of breast cancer (BC) has been demonstrated, suggesting that they may be considered as potential markers of this condition." (PMID 37048701, 2023).
breast carcinoma (continued). "Furthermore, Wnt pathways were found to regulate the transcription of the angiogenic factors interleukin-8 and MMP7, thereby enhancing angiogenesis in pancreatic, prostate and breast cancers." (PMID 36497192, 2022). "C-c motif chemokine ligand 27 (CCL27), a chemokine primarily expressed by keratinocytes, and its enhanced expression activate the extracellular signal-regulated kinase 1/2 (ERK1/2) pathway and in turn overexpress MMP-7 leads to cell invasion and migration of breast cancers." (PMID 36250005, 2022). "MMP7 was a decisive factor in Chinese women with breast cancer." (PMID 35069702, 2021). "Nevertheless, case-control studies, regarding the relationship between the plasma concentration of MMPs, including MMP-7 and the subsequent risk of postmenopausal breast cancer have not demonstrated any dependence." (PMID 33916127, 2021). "Besieds, highly expressed MMP7 can reduce the survival rate of breast cancer." (PMID 35069702, 2021). "We found that up-regulation of KIF3B activates the Wnt signaling via increasing the expression of Dvl2, p-GSK-3βser9, total and nucleus β-catenin, then up-regulation of Wnt signaling target genes such as CyclinD1, C-myc and MMP-7, which are highly expressed in breast cancer." (PMID 33542902, 2020). "XAV-939, an inhibitor of β-catenin accumulation could reverse DKK1 silencing-induced MMP7 expression in breast cancer cells." (PMID 31285694, 2019). "However, some studies argue that SIRT1 suppresses cancer cell migration and invasion, such as, by targeting ARHGAP5 in gastric cancer, by inhibiting the TGF-β/Smad4/MMP-7 axis in breast cancer and by regulating autophagy in CRC." (PMID 31068761, 2019). "FOXC1 promotes metastasis and invasion by inducing MMP7 expression in breast cancer." (PMID 29552326, 2018). "Therefore, KIF3A was demonstrated to mediate the effect of PLCD1 on ERK1/2/β-catenin/MMP7 signalling, at least in part, in breast cancer." (PMID 28423710, 2017). "Interestingly, our cell line data (protein expression and enzyme activity) also demonstrates that there is an MMP7-enriched sub-population of TN breast cancer cell lines recapitulating the patient breast tumor data." (PMID 24143235, 2013). "Other studies support a role of Mmp7 in mammary cancer development and/or progression." (PMID 24304664, 2013). "In addition, in our previous study, we demonstrated that STAT3 and AP-1 participated in regulating Her2 signaling-mediated MMP-7 expression in breast cancer cells." (PMID 20939893, 2010). "In addition, MMP7 overexpression has also been reported for a variety of cancers, including those of the oesophagus, stomach, pancreas, lung, colon/rectum and breast cancer, while S100A4 is a mediator of metastasis,[and references therein,41]." (PMID 19578441, 2009). "Likewise, it has been recently reported that MMP-7 overexpression in breast cancer (MCF-7) cells enhances cellular invasiveness and activation of proMMP-2 and MMP-9." (PMID 17342087, 2007). "Interestingly, a recent immunohistochemistry study has reported expression of MMP-7 in about 50% of human breast cancer cells which correlates with tumour invasion." (PMID 16880790, 2006). "According to the results obtained by our team on MMP-3 and MMP-7, they may appear to be useful as new biomarkers in the primary diagnosis of patients with early stage breast cancer (TNM stage I) and the most common subtypes—Luminal A and Luminal B HER2-negative." (PMID 37048701, 2023). "Therefore, we then investigate whether DKK1 regulates the expression of MMP7 in breast cancer cells." (PMID 31285694, 2019). "In contrast, LEF1 was able to regulate MMP-7 expression and activity in breast cancer cells, whereas another previous study showed that circulating MMP-2 and MMP-9 could be used to potentially classify patients into low risk, high risk, benign disease, and breast cancer." (PMID 24098538, 2013). "MMP-2, MMP-7, and VEGF-A are the major genes that promote metastasis and angiogenesis in breast cancer cells." (PMID 36770598, 2023).
breast carcinoma (continued). "All the treated breast cancer cell lines demonstrated a substantial reduction in MMP-2, MMP-7, and VEGF-A gene expression levels." (PMID 36770598, 2023). "Plasma levels of MMP-7 were significantly higher in Luminal A and Luminal B HER2-negative subtype breast cancer patients as compared to the healthy group." (PMID 37048701, 2023). "The upregulation of different members of the MMP family (e.g., MMP2, MMP3, MMP7 and MMP9) in prostate, gastric and breast cancers, among others, leads to the acquisition of an invasive phenotype." (PMID 36497192, 2022). "In breast cancer, WNT5A from TAMs can induce the expression of MMP-7, resulting in matrix remodeling." (PMID 35847885, 2022). "In models of breast cancer metastases and kidney fibrosis, SIRT1 suppressed EMT by deacetylating Smad4 and thus, repressing TGFβ-induced MMP7." (PMID 33946753, 2021). "S1P induces the expression of MMP2 in endothelial cells, MMP7 in hepatocellular carcinoma cells, and MMP9 in breast cancer cells." (PMID 34262394, 2021). "In breast cancer cells, DKK1 inhibits migration and invasion though suppression of the β-catenin/MMP7 pathway." (PMID 33613114, 2021). "Matrix metalloproteinases (MMPs) such as MMP2, MMP7, and MMP9 are metastasis markers in breast cancer." (PMID 32408199, 2020). "A fusion of the same two genes has been reported in a breast carcinoma, while in one ovarian carcinoma TMEM123 was found fused with MMP7." (PMID 28893231, 2017). "Fibulin-3 for instance is known to suppress ERK pathway via its RGD motif and it has been published that in breast cancer fibulin-3 is downregulated leading to increased ERK and MMP-7 expression." (PMID 28209981, 2017). "Normalized mRNA levels for BC cell lines show that the high-MMP7 expressing TN breast cancer cells (HCC38, HCC70, DKAT, and SUM149) have significantly lower levels of MMP7 mRNA as compared to the other low-MMP7 expressing TN cells as well as no-MMP7 expressing non-TN cells (MCF, T47D)." (PMID 24143235, 2013). "Our previous study demonstrated that heregulin-β-induced MMP-7 expression was regulated by HER2-mediated STAT3 and AP-1 activation in human breast cancer cell lines." (PMID 20939893, 2010). "We have demonstrated that STAT3 and AP-1 are important transcriptional regulators of MMP-7 and MMP-9 in human breast cancer cells previously and STAT3 and AP-1 exert transcriptional regulation functions by binding to their respective elements." (PMID 20939893, 2010). "And in another study, breast cancers induced by Wnt-1 overexpressed a series of MMPs, including MMP-2 and MMP-9, except MMP-7, a long held Wnt target gene in intestinal tumors." (PMID 19586554, 2009). "Matrix metalloproteinase-1 was immunohistochemically detected in 88.3% of breast carcinomas, MMP-2 in 42%, MMP-7 in 87.4%, MMP-9 in 74%, MMP-11 in 89.3%, MMP-13 in 73.3%, MMP-14 in 90%, TIMP-1 in 95%, TIMP-2 in 87% and TIMP-3 in 82.3%." (PMID 17848954, 2007). "The association of hepatocyte growth factor (HGF) with breast cancer was stronger in Estrogen Receptor (ER)-negative patients, while CASP8, CXCL11, MMP7, and C–C motif chemokine 4 (CCL4) were associated with ER-positive breast cancer." (PMID 40665092, 2025). "Furthermore, E2-ERα signaling drives MMP-2, MMP-9, and MT1-MMP upregulation, promoting ECM remodeling and thereby enhancing breast cancer cell invasion and migration, while ERβ has also been found to regulate the expression of MMP-2 and MMP-7." (PMID 41228316, 2025). "Furthermore, the gene knockout mechanism of MMP-2, MMP-7, and MMP-9 shown by CRISPR-Sp cas9 to improve cancer treatment at the gene level will also pave the way for future approaches in the treatment of breast cancer." (PMID 38774755, 2024). "As levels of MMP-7 autoantibodies were not elevated in patients with breast cancer, we excluded it for further analysis in this study." (PMID 33854634, 2021).